TRIM32 (tripartite motif containing 32)
Diseases named in the same sentence as TRIM32 in open-access papers (continued):
Sharing a sentence is not in itself a finding about the gene and the disease.
cancer (26 papers, 2017 to 2025). A tumor composed of atypical neoplastic, often pleomorphic cells that invade other tissues. "TRIM32 protein represents a crucial member of TRIM family that is highly expressed in numerous human cancers, and is associated with a poor prognosis." (PMID 40507857, 2025). "TRIM32 is implicated in diverse biological and physiological processes such as muscle physiology, neuronal differentiation, immunity and cancer." (PMID 33999923, 2021). "Six pDGVs in the PINX1, MOB1A, CLTCL1, PRR5, CCDC136, and TRIM32 genes involved the exact amino acid residues affected by known somatic cancer variants." (PMID 33273457, 2020). "In addition to development and cancer, these findings are also pertinent in limb-girdle muscular dystrophy 2H, an hereditary skeletal muscle disorder caused by TRIM32 mutations, where C-MYC regulation by TRIM32 in myogenic progenitors is implicated." (PMID 38115822, 2023). "A better understanding of TRIM32 function may lead to therapeutic interventions to either increase cell size in patients with mutations in TRIM32 or to limit the growth of cancers that overexpress TRIM32." (PMID 33802079, 2021). "In this study, we found that TRIM32 is highly expressed in a variety of cancer tissues through pan-cancer analysis." (PMID 40507857, 2025). "Bioinformatics analysis showed that TRIM32 is up-regulated in many types of cancers, and exhibits significant prognostic value in CRC." (PMID 40507857, 2025). "In this study, The Cancer Genome Atlas (TCGA) and Gene Expression Omnibus (GEO) database were utilized to analyze the expression of TRIM32." (PMID 40507857, 2025). "Specifically, TRIM14, TRIM25, TRIM32, TRIM44, TRIM59, and TRIM29 exhibit abnormal expression in different cancer types and have been linked to patient prognosis." (PMID 39273003, 2024). "Another study found that TRIM16, TRIM32, TRIM24, TRIM8, TRIM27, TRIM11, and PML are associated with cancer stem cells and the clinical prognosis of RCC, and affect tumor progression." (PMID 36261847, 2022). "In another aspect, although previous reports have demonstrated the involvement of TRIM32 in progression of many types of malignant tumours, its role in PDAC is yet fully investigated." (PMID 34921503, 2022). "The dysregulation of c-Myc in cancer cells promoted TRIM32 expression, which ubiquitinated SIRT4 for the proteasome-dependent degradation, thereby facilitating methionine cycle by reducing the ADP-ribosylation modification of MAT2A." (PMID 36371321, 2022). "Research also revealed that TRIM66, TRIM25 and TRIM32 are involved in TGF-β signaling pathways to promote cancer cell proliferation and invasion." (PMID 36261847, 2022). "The role of TRIM32 in enhancing glycolytic flux is aligned with its role in promoting cancer, but conceptually contradicts Trim32’s role in inhibiting cancer growth." (PMID 33802079, 2021). "TRIM32 mediates DIAP1 levels to prevent muscle cell apoptosis during pupal development, while XIAP is similarly targeted by mammalian TRIM32 to prevent apoptosis of cancer cells." (PMID 33802079, 2021). "Collectively, our data show that TRIM32 is required for cell growth in both normal and tumorous glycolytic tissues, thus providing a novel molecular explanation for the upregulation of TRIM32 in multiple types of cancer cells." (PMID 32223900, 2020). "The multi-faceted roles exhibited by TRIM32 in muscle physiology and cancer seem quite different on the surface." (PMID 32223900, 2020). "As in muscle tissue, the majority of studies on TRIM32 and cancer have focused on identifying substrates that are subject to poly-ubiquitination and subsequent proteasomal degradation." (PMID 32223900, 2020). "In contrast, several studies indicate that TRIM32 is an oncogene, which promotes proliferation of cancer cells." (PMID 28514764, 2017).
cancer (continued). "TRIM32 may be a significant proto-oncogene which exerts a regulatory influence on the occurrence and development of various benign and malignant tumors." (PMID 40507857, 2025). "Moreover, the overexpression of TRIM32 promoted cell proliferation rates, and induced drug resistance in cancer cells." (PMID 41163195, 2025). "It has been reported that TRIM32 can promote the progression of many cancers." (PMID 40507857, 2025). "Taken together, the data suggest that TRIM32-mediated targeting of myc proteins may provide new avenues for stem cell cancer drug therapy." (PMID 33802079, 2021). "TRIM32 has been reported to be involved in cancer development." (PMID 35004288, 2021). "TRIM32 acts as an E3 ubiquitin ligase and has been reported to participate in many human cancers." (PMID 30079558, 2018). "IHC staining confirmed that TRIM32 expression was elevated (36/61, 59%) in GC compared to matched normal gastric tissues, and the staining was mainly located in the nuclei and cytoplasm of cancer cells." (PMID 30079558, 2018). "Finally, USP11 can also control the stability of ARID1A by competing with TRIM32 to determine whether it is cancer-promoting or cancer-suppressing." (PMID 35359344, 2022). "It has been shown in previous studies that the E3 ubiquitin ligases, such as RNF146, TRIM11, TRIM32, TRIM54, TRIM65 and UBE3C promote various cancers by triggering Wnt/β-catenin signaling via degradation of Axin1." (PMID 37379772, 2023). "Although TRIM proteins have been studied in different types of cancer, and some members of the TRIM family have been found to be dysregulated and to participate in the pathogenesis of GC, the possible role of TRIM32 in GC is still unclear." (PMID 30079558, 2018). "In addition, TRIM31, TRIM32, and TRIM47 were reported to play a role in the AKT signaling pathway in cancer." (PMID 36261847, 2022). "TRIM32, TRIM28, and TRIM44 promote cancer progression by activating β-catenin signaling." (PMID 32802046, 2020). "The interactions of the Wnt/β-catenin pathway and other members of the TRIM protein family, such as TRIM29, TRIM28, TRIM32, TRIM33, and TRIM44, may play important roles in the development of human cancers." (PMID 32802046, 2020). "The proteolytic turnover of these proteins may affect signaling pathways independent of glycolytic TRIM32 regulation or may be a compensatory mechanism in response to metabolic shifts in which normal cells can transiently adopt cancer-like metabolism during periods of rapid proliferation." (PMID 32223900, 2020).
infection (18 papers, 2015 to 2025). The state of being infected such as from the introduction of a foreign agent such as serum, vaccine, antigenic substance or organism. "Reduced TRIM32 expression in lung epithelial and tracheal cells increases their susceptibility to infection of influenza A virus." (PMID 33999923, 2021). "The K63-linked ubiquitination of STING mediated by TRIM56 and TRIM32 promotes TBK1–STING interaction upon infection with Sendai virus (SeV) or HSV-1." (PMID 29760876, 2018). "We generated NRCMs with either reduced or elevated levels of TRIM32 by infection with AdshTRIM32 or AdTRIM32 (adenoviral vector encoding TRIM32 cDNA) respectively." (PMID 26884348, 2016). "However, compared with AdshRNA-infected controls, AdshTRIM32 infection-mediated TRIM32 deficiency dramatically exaggerated AngII-induced cardiomyocyte hypertrophy, as was evident by up-regulation of cardiomyocyte surface area (2419±280 compared with 1734±88 μm2; P<0.05)." (PMID 26884348, 2016). "To determine which step in the viral replication cycle is targeted by TRIM32, we first performed a post-entry infection assay." (PMID 38895352, 2024). "We have initially identified TRIM32 in an RNA-seq analysis aimed at identifying TRIM genes whose expression is modulated during ex vivo infection of human primary macrophages with Mtb or BCG." (PMID 37543647, 2023). "To further confirm the involvement of TRIM32 in antimicrobial immunity against Lm infection, we infected WT and Trim32−/− mice via i.p. infection and measured bacterial load at 1 and 3 dpi in the spleen and liver, which were the major organs colonized by Lm." (PMID 37415157, 2023). "Immunoblot analysis showed a significant increase in the rate of LC3-II degradation in TRIM32-expressing cells following infection with Mtb." (PMID 37543647, 2023). "TRIM32 has been shown to promote IFN-β secretion during herpes simplex virus infection via the STING-IRF3 signaling pathway in order to eliminate infection." (PMID 37415157, 2023). "A significant reduction in the number of CFU were observed in TRIM32 expressing THP-1 when compared to GFP expressing THP-1 upon infection with Mtb for 4 days." (PMID 37543647, 2023). "To investigate if Golgi network localization of SseK3-HA during infection depends on TRIM32, we generated TRIM32 null macrophages through the CRISPR-Cas9 method." (PMID 28069818, 2017). "Conversely, AdTRIM32 infection-mediated TRIM32 overexpression markedly attenuated AngII-induced cardiomyocyte hypertrophy compared with AdGFP-infected controls (972±120 compared with 1681±191 μm2; P<0.05)." (PMID 26884348, 2016). "After SVCV infection, some test carps developed hemorrhagic symptoms, relative changes of TRIM32 mRNA at different post-infection (p.i.)time was assessed using qRT-PCR." (PMID 27735853, 2016). "We describe how the E3 ubiquitin ligase, TRIM32, inhibits the activity of the influenza RNA polymerase and defends respiratory epithelial cells against infection with influenza A viruses." (PMID 26057645, 2015). "Additionally, VEEV-TC83-Nluc/Cap studies showed decreased activity in the presence of TRIM32 expression during the early stages of infection, suggesting that TRIM32 affects late VEEV entry by capsid uncoating." (PMID 39599842, 2024). "We observed a modest rescue of infection in the Trim32-depleted cells, suggesting that endogenous TRIM32 may contribute to cell intrinsic suppression of VEEV." (PMID 38895352, 2024). "For instance TRIM32, the first binding partner described for SseK3, is an E3 ubiquitin ligase that is not glycosylated by SseK3 and is not required for the inhibition of NF-κB signaling during the infection of macrophages." (PMID 32366039, 2020). "First, we tested if TRIM32 and the SseK effectors interacted during infection." (PMID 28069818, 2017).
infection (continued). "In order to verify the antiviral potential of TRIM32 in vitro, EPC cells with TRIM32 transient overexpression were infected with SVCV at a multiplicity of infection (MOI) of 0.1, and SVCV production was determined by TCID50 assay at four different p.i. time points." (PMID 27735853, 2016). "TRIM32 deficiency did not alter the level of infection with wild type Sendai or a Sendai-luciferase reporter virus." (PMID 26057645, 2015). "Wild type TRIM32 attenuates infection with the IAV reporter virus." (PMID 26057645, 2015). "Indeed, we found that Trim32 expression restricted VEEV-TC83-GFP infection significantly." (PMID 38895352, 2024). "SseK3 binds to the E3-ubiquitin ligase TRIM32, but the significance of this interaction is unknown since this host protein is not modified by SseK3 and is not necessary for SseK3-dependent inhibition of NF-κB activation during the infection of macrophages." (PMID 32366039, 2020). "During IAV infection, basally expressed TRIM32 targets PB1 for proteasomal degradation, which inhibits infection prior to interferon-mediated effects." (PMID 38895352, 2024). "Next, we established HeLa stable cells expressing TRIM8, TRIM25, TRIM26, TRIM32, and TRIM33 to evaluate their effects on VEEV-TC83-GFP infection." (PMID 39527628, 2024). "Ectopic expression of TRIM32 reduces alphavirus infection, whereas depletion of TRIM32 with CRISPR-Cas9 increases infection." (PMID 38895352, 2024). "TRIM32 expression is upregulated by KSHV during latency, whereas TRIM32 undergoes degradation via the proteasomal machinery during the lytic infection phase." (PMID 39599852, 2024). "These functional studies also identified four factors (TRIM32, TRAF3-IP2, RNF10, and KHLH34) that specifically modulate infection with the H1N1pdm09 virus from the 2009 pandemic." (PMID 29202037, 2017). "First, FLAG-tagged TRIM32 and TRIM65 (a control TRIM family member with established E3 ligase activity) were transfected into A549 cells followed by infection with PR8-Gaussia luciferase reporter virus." (PMID 26057645, 2015). "In contrast, as demonstrated in this study, TRIM32 operates in a more restricted fashion to directly sense an IAV “danger” signal and to restrict infection in a species specific manner." (PMID 26057645, 2015). "Next, the stability of the NLuc/Cap of VEEV was determined in HeLa-TRIM32 or HeLa-Fluc cells by VEEV-NLuc/Cap infection in the presence or absence of cycloheximide." (PMID 38895352, 2024). "TRIM32 expression was downregulated by using two different lentiviral short hairpin RNAs (shTRIM32a and shTRIM32b) in THP1, infected with Mtb and bacterial growth analyzed by CFU counts 4 days after infection." (PMID 37543647, 2023). "TRIM32 is a member of the tripartite motif family, which is characterized by the presence of a RING domain that confers E3 ubiquitin ligase activity and functions as an important immune-regulatory protein in response to pathogen infection." (PMID 37415157, 2023). "The overexpression of TRIM32 significantly decreased SVCV titer at 24 h post-infection, but did not affect the mRNA level of IFN1 with or without SVCV stimulation." (PMID 27735853, 2016). "The results showed that the expression of TRIM32 (mRNA) was highest in the brain, remained stably expressed during embryonic development, and significantly increased following spring viraemia of carp virus (SVCV) infection." (PMID 27735853, 2016). "The exact mechanism of this observation is currently not known, and future studies focusing on SVCV infection of cultures with constitutive or long-term expression of TRIM32 is needed to explain the observed effect." (PMID 27735853, 2016). "Again, VEEV-TC83-GFP infection was strikingly reduced by TRIM32 expression in the absence of TBK1." (PMID 38895352, 2024). "Therefore, TRIM32 is not required for SseK3 to inhibit NF-κB signaling during infection of macrophages." (PMID 28069818, 2017).
infection (continued). "TRIM32 overexpression could significantly decrease the virus titer after 24 h following SVCV infection, this phenomenon was not related to the IFN1 signaling pathway." (PMID 27735853, 2016). "However, SseK3 still inhibited NF-κB activation during infection of macrophages lacking TRIM32." (PMID 28069818, 2017).
myopathy (7 papers, 2012 to 2023). A disease of the muscle in which the muscle fibers do not function properly. "Together with the previously published report, our results indicate that a homozygous deletion variant is associated with pathogenicity of TRIM32-related myopathy." (PMID 33485293, 2021). "A total of 27 different mutations have been reported in patients with TRIM32-related myopathy, including one nonsense, ten missense, nine frameshifts, two small deletion, and five large deletion variants." (PMID 33485293, 2021). "LGMD2H is a relatively mild form of myopathies caused by mutations in the gene encoding Tripartite motif-containing protein 32 (TRIM32), a well-known E3 ubiquitin ligase." (PMID 33841177, 2021). "Different phenotypes produced by mutations in TRIM32, even in the same region of the gene, has similarly been reported in other myopathies associated with mutation in other genes such as MYH7." (PMID 30823891, 2019). "AMBRA1 interacts with Tripartite motif-containing 32 (TRIM32) that is crucial as well, and indeed its deletion causes myopathy with neurological complications, both superimposable with the phenotype observed in patients with limb-girdle muscular dystrophy 2H (LGMD2H)." (PMID 33363161, 2020). "Altogether, these results coming from cell and animal models, support the hypothesis that TRIM32 is involved in control of myogenesis and that premature senescence underlies myopathy in LGMD2H." (PMID 30823891, 2019). "Decreased level of p62/SQSTM1 in muscle form TRIM32-myopathy patients supports an increased autophagy." (PMID 30823891, 2019). "Together, these results suggest that increased autophagic flux is present in TRIM32-related myopathy." (PMID 30823891, 2019). "We also provide clinical evidence of TRIM32-related myopathy patients presenting muscular weakness together with BBS clinical manifestations, but to elucidate responsible factors additional studies must be carried out." (PMID 30823891, 2019). "To address this, we firstly performed extensive histological analyses on our established TRIM32 null mice to determine whether these mutant mice develop a similar myopathy as seen in human LGMD2H patients." (PMID 22299041, 2012). "Finally, we provided evidence that TRIM32 knock-out mice developed a myopathy similar to that presented by LGMD2H patients and that muscle regeneration in these mice was greatly delayed and impaired." (PMID 22299041, 2012).
neurodevelopmental disorder (4 papers, 2018 to 2023). A behavioral and cognitive disorder with onset during the developmental period that involves impaired or aberrant development of intellectual, motor, or social functions. "Genome-wide studies have found rare copy number variants (CNVs) interfering with the TRIM32 gene at the 9q33.1 locus in some individuals with neurodevelopmental disorders." (PMID 36297015, 2022). "The associated SNPs map at the highly conserved ASTN2/BRINP1 locus at chr9q33.1–33.2, which contains five genes (ASTN2, BRINP1, TRIM32, TLR4 and C5) that have been previously associated with neurodevelopmental disorders (reviewed in29)." (PMID 34267256, 2021). "In addition to including the entire TRIM32 gene, all 7 deletions also include part of the ASTN2 gene, which encodes astrotactin 2, a brain protein that may be involved in neuronal migration and is associated with neurodevelopmental disorders." (PMID 37217920, 2023).
neuromuscular disease (2 papers, 2021 to 2023). "Analysis of neuromuscular disease V3-panel NGS showed that the proband was a homozygote of a novel missense mutation (TRIM32:c.1700A > G, p.H567R), and copy number analysis of the TRIM32 gene by RT-PCR revealed that one allele was deleted." (PMID 37217920, 2023).
bacterial infection (1 paper, 2023). "Our discovery of TRIM32 as a host factor that functions to control S. Typhimurium virulence has expanded the role of these E3 Ub ligases in defense against bacterial infection." (PMID 38817622, 2023).
neurodegenerative disease (1 paper, 2021). A disorder of the central nervous system characterized by gradual and progressive loss of neural tissue and neurologic function. "Based on these findings, the increase in TRIM32 and concomitant decrease in CXX1B may be sensitive early indicators of developing Ubqln2-dependent neurodegenerative disease." (PMID 33277362, 2021).
TRIM32 also shares sentences with these, for which no sentence is quoted: nervous system diseases (2 papers); prostate carcinoma (2); schizophrenia (2); squamous cell carcinoma (2); absence seizures (1); acrocallosal syndrome (1); alcohol dependence (1); atopic dermatitis (1); atrial fibrillation (1); Becker muscular dystrophy (1); brain tumor (1); colitis (1); collagenopathy (1); congenital myopathy (1); COVID-19 (1); diabetes mellitus (1); dyslipidemia (1); Emery-Dreifuss muscular dystrophy (1); entrapment neuropathies (1); fatty liver disease (1); Filaminopathy (1); gastric tumour (1); genetic diseases (1); heart diseases (1); hypertrophic cardiomyopathy (1); Infertility (1); inflammation (1); laminopathy (1); Leber congenital amaurosis (1); multiple sclerosis (1).
A further 17 diseases each share a sentence with TRIM32 in 1 paper.